BRCA1 (BRCA1 DNA repair associated)
Diseases named in the same sentence as BRCA1 in open-access papers (continued):
Sharing a sentence is not in itself a finding about the gene and the disease.
ovarian carcinoma (continued). "Knowledge of the uptake and breast and ovarian cancer-preventive and survival effects of bilateral risk-reducing mastectomy (BRRM) and salpingo-oophorectomy (RR-BSO) in female BRCA1/2 carriers is essential for optimized decision-making." (PMID 40974500, 2025). "Carriers of germline pathogenic variants (PVs) in the BRCA1 and BRCA2 genes are at higher risk of developing breast and ovarian cancer than the general population." (PMID 40399999, 2025). "Both BRCA1 and BRCA2 alterations serve as a pathogenic basis for HBOC and are associated with increased susceptibility to breast or ovarian cancer." (PMID 40249378, 2025). "We meta-analyzed >22 million variants for 398,238 women from the Ovarian Cancer Association Consortium (OCAC), UK Biobank (UKBB) and Consortium of Investigators of Modifiers of BRCA1/BRCA2 (CIMBA) to identify novel HGSOC susceptibility loci." (PMID 41266372, 2025). "BRCA1/2 mutations constituted approximately 80% of cases in Chinese ovarian cancer patients harboring at least one HRR-related pathogenic mutation, with mutually exclusive occurrences of BRCA1/2 mutations (P < 0.001)." (PMID 40687614, 2025). "For example, germline PSVs in the BRCA1 and BRCA2 genes are associated with a significantly increased risk of breast and ovarian cancers in women, and breast and prostate cancers in men." (PMID 40779059, 2025). "For example, loss of CDK12/cyclin K-mediated transcriptional elongation of genes in the HR DNA repair pathway, including BRCA1, has previously been demonstrated in ovarian cancers." (PMID 40504161, 2025). "The “high-penetrance” genes BRCA1 and BRCA2 were identified by linkage studies in the 1990’s; protein truncating variants in these genes confer a substantial lifetime risk of epithelial ovarian cancer as well as breast cancer and other cancers." (PMID 39939714, 2025). "BRCA1- and BRCA2-associated hereditary breast and ovarian cancers are characterized by an increased risk of developing breast cancer in both men and women, as well as ovarian, fallopian tube, and primary peritoneal cancers." (PMID 40427158, 2025). "In particular, women with mutations in BRCA1 (located on chromosome 17q21) or BRCA2 (located on chromosome 13q12.3) have an increased risk of developing breast and ovarian cancer." (PMID 40427158, 2025). "Response to PARPi has initially been observed in ovarian cancer patients with alterations in the genes BRCA1 and BRCA2,17, 18 but later studies reported that clinical response was also observed in patients with BRCA1/2 wildtype status." (PMID 40278800, 2025). "The reliability and validity of the MICRA-J were evaluated in individuals who underwent BRCA1/2 testing for hereditary breast and ovarian cancer diagnosis." (PMID 40900191, 2025). "In ovarian cancer, 79 genes were upregulated and 123 were downregulated in BRCA1-mut cancers, and five were upregulated and seven were downregulated in BRCA2-mut cancers." (PMID 40647506, 2025). "Taken together, we demonstrate that methylstat mitigates positive selection of either PARPi-resistant or BRCA1-proficient ovarian cancer cells under olaparib treatment." (PMID 39915607, 2025). "Identifying pathogenic variants (PVs) in BRCA1 and BRCA2 in epithelial ovarian cancer is crucial for guiding genetic counseling and therapeutic decision-making." (PMID 41425725, 2025). "PARP inhibitors, which are associated with BRCA1/2 mutations that result in homologous recombination DNA repair (HRR) deficiencies, are one of the treatment strategies used in targeted ovarian cancer therapy." (PMID 40405479, 2025). "Defects in the DNA repair pathways, such as mutations in BRCA1 and BRCA2, can enhance the PARP1 activity in breast and ovarian cancers." (PMID 41219748, 2025).
ovarian carcinoma (continued). "The genes most commonly affected in hereditary breast and ovarian cancer are the BRCA1 and BRCA2 genes." (PMID 40303990, 2025). "BRCA1 and BRCA2 are the most frequently mutated genes in hereditary breast and ovarian cancer syndromes; loss of BRCA1 and BRCA2 is indeed associated with a lifelong increased incidence of breast and ovarian cancer of ~80% and ~25–50%, respectively." (PMID 39927794, 2025). "In contrast, breast epithelial tissue from women with germline mutations in the BRCA1 or BRCA2 genes exhibits DNA repair defects, leading to an elevated risk of breast and ovarian cancer, as well as premature aging." (PMID 41294748, 2025). "Deleterious mutations in BRCA1 or BRCA2 lead to defects in DNA damage repair due to homologous recombination deficiency, resulting in a high penetrance for both breast and ovarian cancer following an autosomal-dominant inheritance pattern." (PMID 40405286, 2025). "Regarding ovarian cancer, the risk associated with the presence of a BRCA pathogenetic variant gene in the case of BRCA1 and BRCA2 is 44% (95% CI = 36% to 53%) and 17% (95% CI = 11% to 25%), respectively." (PMID 41092066, 2025). "Germline mutations in BRCA1 and BRCA2 significantly increase the susceptibility to both breast and ovarian cancer, as well as other cancers including pancreatic and prostate cancers." (PMID 41142596, 2025). "These founder alleles account for over 80% of all pathogenic mutations in BRCA1 and BRCA2 genes detected in a series of 1018 Polish families with hereditary breast and/or ovarian cancer." (PMID 40002208, 2025). "BRCA1 alterations were particularly common in ovarian cancer (13.8%), while BRCA2 was prevalent in prostate cancer (8.3%)." (PMID 40420266, 2025). "To gain a better understanding, we investigated the comprehensive cellular consequences of MX treatment in HR-deficient BRCA1-mutant UWB1.289 (BRCA1−) and HR-proficient (BRCA1+) UWB1.289 ovarian cancer cells using quantitative shotgun proteomics." (PMID 41283651, 2025). "Prior studies have elucidated key genes in the homologous recombination pathway, including BRCA1, BRCA2, RAD51, and PALB2, that commonly have pathogenic germline variants and/or somatic mutations in breast and ovarian cancers." (PMID 40327608, 2025). "Individuals with inherited mutations in BRCA1 or BRCA2 have a significantly higher risk of developing breast and ovarian cancers compared with the general population." (PMID 39996890, 2025). "Furthermore, about potential relationship between BRCA1/2 genes and ovarian cancer, we know that BRCA1/2 mutations may directly reshape the vaginal environment by altering epithelial turnover, immune signaling, hormone regulation, and mucosal barrier integrity." (PMID 41148804, 2025). "Oncology research on BRCA1 and BRCA2 mutations and their association with PARP inhibitors is still very active, especially in cases of breast and ovarian cancer." (PMID 40141415, 2025). "These BRCA1/BRCA2 mutations, linked to hereditary breast and ovarian cancers, lead to a distinct cancer phenotype." (PMID 40864792, 2025). "In cells proficient in homologous recombination (HR), these lesions are repaired via BRCA1/2-mediated pathways; in HR-deficient cells, including many BRCA-mutated or HRD-positive ovarian cancers, they result in cell death through synthetic lethality." (PMID 41541937, 2025). "Incorporating family-history-based BRCA1/2 testing into breast and ovarian cancer screening programs is cost-effective in China and warrants promotion." (PMID 40567951, 2025). "Women with BRCA1 and BRCA2 mutations have a higher risk of developing breast and ovarian cancers, which tend to occur at younger ages." (PMID 41333220, 2025). "Through comprehensive screening, we demonstrated that the mutant IDH1 inhibitor ivosidenib significantly enhances the sensitivity of BRCA1/2-proficient breast and ovarian cancer cells to PARP inhibitors (PARPi)." (PMID 40299557, 2025).
ovarian carcinoma (continued). "An example of this is finding pathogenic variants in the BRCA1/BRCA2 genes which can cause hereditary breast and ovarian cancer and identification directly impacts therapeutic planning for the patient." (PMID 39945861, 2025). "BRCA1 has been shown to induce apoptosis in breast and ovarian cancer cells by activating the HRAS‐MEKK4‐JNK‐FasL/Fas‐caspase‐9 cascade." (PMID 40186402, 2025). "Given the effectiveness of poly(ADP-ribose) polymerase inhibitors (PARPi) in HRD-related cancers such as BRCA1/BRCA2-mutated breast and ovarian cancers, this study suggests PARPi as a potential treatment for EC." (PMID 40948682, 2025). "BRCA1 and BRCA2 tumor suppressor genes are primarily linked with hereditary breast and ovarian cancers and with other malignancies to a lesser extent." (PMID 40162152, 2025). "Our study identified 19/728 carriers (2.6%) of pathogenic HDR gene variants, including 15 truncating variants, of which 4 were in BRCA1 or BRCA2 (0.5%) and 4 were in BRIP1 or RAD51D, two other genes associated with high ovarian cancer risk." (PMID 39440754, 2025). "A significant breakthrough in biomarker research is the discovery of BRCA1 and BRCA2 germline mutations, which strongly indicate hereditary breast and ovarian cancers." (PMID 40636286, 2025). "In ovarian cancer, 79 transcripts were upregulated and 123 were downregulated in BRCA1-mut cancers, while five were upregulated and seven were downregulated in BRCA2-mut tumors." (PMID 40647506, 2025). "BRCA1 deficiency results in GPX4 accumulation, conferring ferroptosis resistance and facilitating ovarian cancer progression." (PMID 40342999, 2025). "It should be noted that annotating samples as HRD and HRP based on defects in BRCA1/2 genes provided almost identical separation in progression-free survival for the 25 PARPi-treated ovarian cancers to that yielded by HRProfiler." (PMID 40327608, 2025). "Background/Objectives: Mutations in the BRCA1 and BRCA2 genes are well-known risk factors for ovarian cancer." (PMID 40869932, 2025). "As BRCA1-methylated ovarian cancer shows similar clinicopathological characteristics to BRCA1m ovarian cancer, researchers have begun investigations on its influence on patient survival." (PMID 40869932, 2025). "Genomic assays for detecting BRCA1/2 pathogenic variants and genomic scars are widely utilised as primary predictive biomarkers for assessing the efficacy of PARP inhibitors in ovarian cancer patients." (PMID 40069561, 2025). "BRCA2 and BRCA1 also reached this level for ovarian cancer, BRCA2, ATM, and CHEK2 for prostate cancer, and ATM for pancreatic cancer." (PMID 40073867, 2025). "Germline mutations in canine BRCA1 and BRCA2 have been associated with a higher risk of CMTs, analogously to their role in human breast and ovarian cancers." (PMID 40004231, 2025). "BRCA1 and BRCA2 play an important role in the repair of double-stranded DNA (dsDNA) breaks through homologous recombination, and women with BRCA1 or BRCA2 gene mutations are predisposed to cancers such as breast and ovarian cancer." (PMID 40243501, 2025). "Women with a BRCA1/2 germline pathogenic variation [GPV] have an increased risk of developing breast and ovarian cancer that is diagnosed at an early age." (PMID 40427184, 2025). "BRCA1 and BRCA2 mutations are widely recognised as significant risk factors for hereditary breast and ovarian cancers, accounting for a substantial proportion of these malignancies." (PMID 40949480, 2025). "Specifically, HRDsig can identify BRCA1 promoter hypermethylation in ovarian cancer, a key epigenetic alteration that leads to silencing of the BRCA1 gene and contributes to HRD." (PMID 41248118, 2025). "The use of genetic biomarkers involves detecting specific gene mutations or alterations, such as BRCA1 and BRCA2 mutations in breast and ovarian cancer." (PMID 39996991, 2025).
ovarian carcinoma (continued). "In ovarian cancer, BRCA1-mut cancer genes such as AIF1, CD8A, and BST1 showed detrimental prognosis, while in BRCA2-mut ovarian cancer, SEC61A2 and IGFBP3 were associated with shorter survival." (PMID 40647506, 2025). "Second, the cohort was predominantly female and of Russian ethnicity, reflecting the high prevalence of BRCA1/2-related breast and ovarian cancers, but limiting generalizability to other racial and ethnic groups." (PMID 40834323, 2025). "Several oncogenes frequently mutated in endometrial and ovarian cancer (ARID1B, ATM, BRCA1, CHD2, POLE, and PMS2) were also present in LMS." (PMID 39691991, 2025). "BRCA1 and BRCA2 germline mutations are linked to a high percentage of hereditary breast and ovarian cancers." (PMID 40904409, 2025). "Mutations in exon 11 of both BRCA1 and BRCA2 have drawn considerable attention because of their potential impact on ovarian cancer outcomes, particularly disease onset and progression." (PMID 40427158, 2025). "Although the focus of BRCA1 has historically been on breast and ovarian cancer, BRCA1 has been found to play a novel role in regulating embryonic brain development and postnatal brain size." (PMID 41347767, 2025). "Several studies have shown that incorporating BRCA1/2 testing in population-based breast and ovarian cancer screening is cost-effective in some high-income countries." (PMID 40567951, 2025). "For instance, in BRCA1-mut ovarian cancer, KTR14, KRT16, CXCL9, and CFD were highly upregulated (more than 4-fold change), and in BRCA2-mut ovarian cancers, TSPAN7 and CDKN2C were clearly upregulated (more than 2-fold change)." (PMID 40647506, 2025). "Therapeutic benefits of PARPis have been observed in patients with cancer carrying germline mutations in the BRCA1 and BRCA2 genes, particularly for ovarian cancer cases." (PMID 41223417, 2025). "Previous studies from other countries report different frequencies of BRCA1/2 mutations among DCIS cases, i.e., depending on ethnic group, the age of diagnosis, the proportion of cases with a family history of breast and/or ovarian cancer." (PMID 40002208, 2025). "Specific genetic mutations in oncogenes, such as BRCA1 and BRCA2, are linked to various cancers, including breast and ovarian cancer." (PMID 41180630, 2025). "Materials and methods: Patients with advanced stage III-IV epithelial ovarian cancer who had deleterious BRCA1 or BRCA2 were analyzed." (PMID 40075604, 2025). "This review explores the role of the BRCA1 and BRCA2 genes—traditionally associated with breast and ovarian cancers—in the context of OSCC." (PMID 40224184, 2025). "The identification of pathogenic variants in BRCA1 and BRCA2 is a critical predictive biomarker for the use of PARP inhibitors in women with epithelial ovarian cancer." (PMID 40805236, 2025). "Population studies of mutations in high-penetrance genes, such as BRCA1 and BRCA2, are crucial due to their strong association with breast and ovarian cancer." (PMID 40071159, 2025). "In recent years, increasing research efforts have been directed towards exploring BRCA1/2 testing strategies for all breast or ovarian cancer patients and for the general population." (PMID 40567951, 2025). "Risk factors include, among others, genetic predispositions (e.g., BRCA1 and BRCA2 gene mutations in breast and ovarian cancer), hormonal disorders, age, lifestyle, obesity, and environmental factors." (PMID 40647471, 2025).
ovarian carcinoma (continued). "Despite historical classification of ovarian cancer as poorly immunogenic, accumulating data show that TILs expressing PD‐1 correlate with overall survival and response to ICIs, particularly in BRCA1/2-mutant HGSC tumors with high PD‐L1 expression." (PMID 40877861, 2025). "Breast and ovarian cancers are significant global health challenges, with inherited variations in breast cancer gene 1 (BRCA1) and breast cancer gene 2 (BRCA2) substantially increasing the risk, aggressiveness, and early onset of these diseases." (PMID 40071159, 2025). "Several Latin American countries have published studies on BRCA1 and BRCA2 mutations in breast and ovarian cancer patients, offering valuable insights into regional mutation patterns." (PMID 40710012, 2025). "A recent survey on genetic testing and counseling practices for women with breast and ovarian cancer in Asia shows that BRCA1-2 testing and counseling are less commonly offered in Asian countries compared to Western regions." (PMID 41463165, 2025). "In contrast, we show that methylstat alone had cytotoxic effects on both, PARPi-sensitive and PARPi-resistant ovarian cancer cells, while additionally potentiating the effect of olaparib among PARPi-resistant, PARPi-sensitive and BRCA1-proficient cell lines." (PMID 39915607, 2025). "We found that 69 and 10 of our upregulated genes in BRCA1-mut breast and ovarian cancer, respectively, were expressed on the cell surface." (PMID 40647506, 2025). "The aim of this study was to investigate if female BRCA1/2 GPV carriers have an increased risk of malignancies other than breast and tubal/ovarian cancer at an early age." (PMID 40427184, 2025). "This is the first study on BRCA1/2 analysis in breast and ovarian cancer cases in the Jewish community of Rome." (PMID 40563557, 2025). "For instance, breast epithelial cells in women with genetic defects in breast cancer type 1 (BRCA1) or BRCA2 genes exhibit reduced DNA repair capacity, resulting in an increased risk of breast and ovarian cancer, as well as accelerated aging." (PMID 41294748, 2025). "In the early 1990s, both BRCA1 and BRCA2 were identified as cancer susceptibility genes in patients with early-onset breast and ovarian cancer." (PMID 40988318, 2025). "In the case of patients with ovarian cancer, it is recommended to start molecular diagnostics with BRCA1/2 gene sequencing." (PMID 40429755, 2025). "Germline mutations in the BRCA1 and BRCA2 genes, which are ovarian cancer susceptibility genes, are common causes of HRRD." (PMID 41223417, 2025). "In ovarian cancer, BRCA1/BRCA2 HRD detection is concordant across 20 assays, but non-BRCA HRD varies (correlation 0.4–0.9), risking 20% missed cases." (PMID 40864792, 2025). "BRCA1/2 mutations, both germline and somatic, remain the best-validated biomarkers of PARP inhibitor benefit in ovarian cancer." (PMID 41541937, 2025). "Further, the combination treatment also showed synergistic activity in two other BRCA1/2 wild‐type ovarian cancer cell lines, OAW42 and A2780." (PMID 40089867, 2025). "Individuals inheriting deleterious variants in either BRCA1 or BRCA2 exhibit elevated susceptibilities to various malignancies, notably breast and ovarian cancers, along with other malignancies." (PMID 38809921, 2024). "Mutations in the BRCA1 and BRCA2 genes significantly increase the risk of breast and ovarian cancers, with ovarian cancer typically associated with a poor prognosis." (PMID 39272660, 2024). "The objective of this study was to identify and classify the spectrum of mutations found in the BRCA1 and BRCA2 genes associated with breast and ovarian cancer in female patients in Romania." (PMID 38785549, 2024). "The role of the epigenetic silencing of BRCA1/2 has been well described in breast and ovarian cancer, but in pancreatic cancer has yet to be elucidated." (PMID 38577595, 2024).